PLK1 (polo like kinase 1)
Diseases named in the same sentence as PLK1 in open-access papers (continued):
Sharing a sentence is not in itself a finding about the gene and the disease.
cancer (continued). "Keeping these barriers in mind, our study aimed to identify the phlorotannins, compounds from edible brown algae, as therapeutic agents against the receptor protein (PLK-1) that is involved in mitotic cell division in the cell proliferation processes of cancer cells." (PMID 37570823, 2023). "Furthermore, we treated the cells with a highly selective PLK1 inhibitor, volasertib, which potently reduced cell viability in six cancer cell lines with a significantly lower IC50 value than that in normal cell lines." (PMID 37958642, 2023). "Here, we report the identification of the first allosteric inhibitor of Plk1 PBD, called Allopole, a prodrug that can disrupt intracellular interactions between PBD and its cognate phospholigands, delocalize Plk1 from centrosomes and kinetochores, and induce mitotic block and cancer cell killing." (PMID 37603740, 2023). "Moreover, PLK1 phosphorylates components of condensin in cultured human cancer cells, facilitating chromosome condensation and segregation." (PMID 36611980, 2023). "Plk1 overexpression has been discovered in cancer-infected nude mouse cells." (PMID 36865478, 2023). "In addition, PLK1 expression, which is observed in various malignant tumors, often suggests poor prognosis." (PMID 36951624, 2023). "Additionally, we found that the knockdown of UBE2C and PLK1, respectively, can reduce the proliferation and migration capacity, and induce the cell cycle arrest and apoptosis of pan-cancer cell lines, which was consistent with the results of previous studies." (PMID 37958642, 2023). "The plasmid containing the Cas9 gene and the gene encoding sgRNA can be introduced into target cells to form the CRISPR–Cas9 gene knockout system, which can knock out the PLK1 gene of target cells, promote the apoptosis of cancer cells and inhibit the proliferation and migration of cancer cells." (PMID 38140096, 2023). "PLK1 and TOP2A are both implicated in cancer and serve as targets for chemotherapy." (PMID 37893069, 2023). "Interestingly, PLK1 has been confirmed suitable for cancer therapy due to its function in regulating contraction of postmitotic smooth muscle cells." (PMID 37313409, 2023). "For the first time, we demonstrated that CR treatment could inhibit cancer cell growth by inhibiting the PLK1/CDK1/Cyclin B axis across ten cancer cell lines based on gene expression profile analysis." (PMID 37007025, 2023). "Overexpression of polo-like kinase 1 (PLK1) has been found in many different types of cancers." (PMID 36676076, 2023). "Therefore, PLK1 is overexpressed in different types of cancer, such as colon, stomach, pancreatic, head and neck, ovarian, and breast." (PMID 38067203, 2023). "PLK1 directly phosphorylates Orc2 to promotes DNA replication, while PLK1 depletion impairs DNA replication, thereby inhibiting in vitro S-phase progression in cancer cells." (PMID 37788997, 2023). "Therefore, phosphorylation of FoxM1 at Ser25 by PLK1 should be specified for cancer metastasis and direct activation of mesenchymal genes to acquire invasiveness." (PMID 37968723, 2023). "We propose that combining PLK1 inhibitors with KIF18A inhibitors may prove particularly effective in treating cancers with complex karyotypes." (PMID 37639469, 2023). "The broad cancer-promoting functions of FOXK1 warrant further investigation to characterize the significance of this colocalization of PLK1 and FOXK1 and to determine what role it may play in tumor progression." (PMID 37174744, 2023). "PLK1 is a key regulator of cell mitosis and is overexpressed in various of cancers." (PMID 37313229, 2023). "The role of PLK1 is not confined to mitosis: it is also implicated in cell motility, epithelial-to-mesenchymal transition, and cancer." (PMID 36626982, 2023).
cancer (continued). "PLK-1 is well known to express an oncogenic effect in various types of cancer." (PMID 37570823, 2023). "In addition, PLK1 is a regulator of the cancer stem cell (CSC) phenotype whose inhibition prevents the stemness phenotype in cancer cells." (PMID 37447165, 2023). "Inhibition of PLK1 leads to cellular G2/M blockade, inhibition of proliferation, and downregulation of Survivin expression to promote apoptosis, making it possible to use PLK1 inhibitors as a potential therapeutic tool to treat cancer." (PMID 37415742, 2023). "We and others have shown that inhibition of PLK1 impaired TCTP phosphorylation, suggesting that a functional PLK1/TCTP axis could be critical for cancer progression." (PMID 37842235, 2023). "These targets are essential in various key cancer-related signaling pathways, including PLK1." (PMID 38201556, 2023). "In addition, based on our previous study, the analysis of tumor tissue single-cell transcriptome data showed that the expressions of UBE2C and PLK1 have a similar significant upregulation trend in cancer cell clusters (CSs)." (PMID 37958642, 2023). "Beyond its role in cell-cycle dysregulation, PLK1 significantly promotes cancer progression via metabolic reprogramming, including enhancing the flux of the pentose phosphate pathway and directing glucose to pathways involved in the synthesis of macromolecules." (PMID 37958623, 2023). "Our finding that KIF18A, the SAC and PLK1 are highly interdependent suggests that PLK1 may also be a target of choice in cancers with complex karyotypes." (PMID 37639469, 2023). "CDCA8, AURKB and PLK1 were also three hub ICPs in multiple kinds of cancers." (PMID 37770497, 2023). "Furthermore, the downregulation of PLK1 expression typically reduces the proliferation of diverse cancer cells." (PMID 37958623, 2023). "Therefore, we first analyzed different types of alterations including mutations, structural variations, amplifications, and deep deletions in the PLK1 gene in using the TCGA cancer datasets with the cBioPortal portal." (PMID 36618405, 2022). "Importantly, PLK1 function is also essential for centrosome maturation and aberrant PLK1 activity can lead to serious diseases in humans, including cancer." (PMID 35912107, 2022). "In addition to its role in mitosis, PLK1 has a unique function in regulating cancer cell metabolism, which promotes the growth of cancer cells." (PMID 36297281, 2022). "PLK1 has been validated as a molecular target and a prognostic factor in a variety of cancers." (PMID 36297407, 2022). "The data gathered may then be used to improve the already existing spectrum of PLK1 inhibitors by designing a new generation of small molecule inhibitory drugs targeting PLK1 for clinical cancer trials." (PMID 34759346, 2022). "By now, PLK1 inhibitors are undergoing clinical trials of various cancers." (PMID 35983074, 2022). "In addition, PLK1 also has roles in meiosis, including regulating cancer cell invasiveness and preventing cancer cell apoptosis." (PMID 35756492, 2022). "Whether PLK1 can exert effects in the pathological process of various cancers through some similar molecular mechanisms has yet to be explored." (PMID 36618405, 2022). "PLK1 is a common therapeutic target and overexpressed in a variety of cancers, and targeting PLK1 may enhance the host's innate immune response." (PMID 36393974, 2022). "In addition, in vitro treatment with PLK1 inhibitors upregulated the expression of HLA molecules in different cancer cells." (PMID 35719948, 2022). "Nowadays, PLK-1 is considered a cancer therapeutic target with clinical therapeutic value." (PMID 36457496, 2022).
cancer (continued). "Answering these questions should clarify whether the expression levels of the anti-apoptotic proteins and PLK1 can be used to help clinicians to select those cancer patients who may benefit from combination treatments." (PMID 35745782, 2022). "An increase in PLK1 expression is well documented in numerous cancers." (PMID 35053604, 2022). "In addition to its role in the activity of tumor suppressors and oncogenes, PLK1 has a distinctive function in regulating cancer cell metabolism, promoting the growth of cancer cells." (PMID 36297281, 2022). "Therefore, HN1L promoted ESCC progression by activating AP-2γ/PLK1 signaling, which was a novel cancer-promoting mechanism of HN1L." (PMID 36476988, 2022). "PLK1 is overexpressed in various cancers, and its expression levels correlate with poor prognosis." (PMID 34759346, 2022). "Moreover, in order to learn the differences of PLK1 mRNA expression in cancer and normal tissues, we analyzed the expression levels of PLK1 mRNA in different tumor tissues and normal tissues through the Oncomine website." (PMID 36618405, 2022). "Taken together, these results suggested that β-carboline-3-carboxylic acid dimers could arrest the cell cycle by suppressing TK1, DBF4, CCNA2, CDK2, and PLK1, together with influencing some cancer-related pathways to inhibit MG-63." (PMID 36325324, 2022). "Since PLK1 expression is a strong negative indicator of prognosis in NSCLC and is higher in metastatic NSCLC, we studied whether active PLK1 drives cancer metastasis." (PMID 35379935, 2022). "Considering the pleiotropic roles of PLK1 in many cellular pathways whose involvement in cancer has been clearly demonstrated, PLK1 is a potential therapeutic target and in the last decade various PLK1 inhibitors have been developed by drug companies and academic research groups." (PMID 35719948, 2022). "Therefore, high expression of PLK1 is correlated with clinical outcomes in several cancers, including metastatic cancers." (PMID 35379935, 2022). "Finally, siRNAs targeting PLK1 or PD‐L1 induce robust gene silencing in cancer cells, and downregulation of PD‐L1 restores the immunological surveillance of T cells in TME." (PMID 35665496, 2022). "Inhibition of PLK1 has been extensively explored as a therapeutic strategy against cancer." (PMID 35745782, 2022). "In addition, PLK1 has also been shown to be overexpressed in various types of cancers, including breast cancer, rectal cancer, colorectal cancer, pancreatic cancer, ovarian cancer, and lung cancer." (PMID 35563642, 2022). "Further, as PLK1 is overexpressed in a variety of cancers, the combination of PLK1 inhibition and PD-L1 blockade may have broad application." (PMID 35871223, 2022). "On the contrary, PLK1 inhibition by MLN0905 promotes senescence in a variety of cancer cells." (PMID 36065138, 2022). "The overexpression of PLK1 appeared in various cancers with poor prognosis and survival." (PMID 35840978, 2022). "In addition, we also used GEPIA2 to investigate the expression of CCNB1 and PLK1 in a variety of other cancers, and the results demonstrated that they were highly expressed in most tumor tissues." (PMID 35456460, 2022). "Moreover, the pretreatment of tumor cells with 100 nM BI6727 reduced the IC50 of Olaparib by 10-fold to 5.7 μM, indicating that, similar to previous cancer cell lines, PLK1 inhibition strongly sensitizes patient-derived tumor cells to Olaparib." (PMID 36142803, 2022). "claimed that PLK1 could be a universal tumor antigen recognized by cytotoxic T lymphocytes for cancer immunotherapy in murine tumor models." (PMID 36618405, 2022). "PLK1 is a promising target for inhibiting mitosis in cancer cells." (PMID 35699421, 2022). "Indeed, mutKRAS cancer cells have been shown to be sensitive to PLK1 inhibition, further demonstrating PLK1 as a downstream target of mutKRAS." (PMID 35805073, 2022).
cancer (continued). "A large number of newly-presented literatures have reported that aberrant expression of PLK1 may lead to many clinical diseases, especially cancers." (PMID 36618405, 2022). "Indeed, hindering PLK1 by using blocking antibodies, genetic depletion and pharmacological molecules negatively affects cancer cell proliferation and results in the induction of apoptosis." (PMID 35563769, 2022). "In addition, depletion of PLK1 expression resulted in inhibition of CA in hydroxyurea-treated centrosome amplified U2OS cells, suggesting overexpression of PLK1 in cancer contributes to CA." (PMID 35053604, 2022). "PLK1 inhibition induces cancer cell death while also upregulating PD-L1 expression of surviving cancer cells, thereby providing the opportunity to target surviving cancer with PD-L1 antibody-conjugated nanoparticles (benefiting cancer otherwise having no established receptors for drug delivery)." (PMID 35871223, 2022). "Polo-like kinase 1 (PLK1) is another tumor-promoting factor in cancer." (PMID 35765040, 2022). "Our recent study demonstrated that PLK1 itself drives cancer metastasis." (PMID 35379935, 2022). "Furthermore, some of the PLK1 inhibitors are in clinical trials and have demonstrated promising results in the treatment of many types of cancer." (PMID 35563642, 2022). "Next, we used the model to study the effect of Plk1 depletion on different cancer cell lines." (PMID 34887439, 2021). "Additionally, the overexpression of PLK1 in tumor cells was shown to activate cancer stem cells (CSCs), with the cluster of differentiation 44 (CD44) surface marker mostly being expressed." (PMID 34063946, 2021). "Thus, PLK1 inhibition normalized aberrant ZFP36/TTP activity in cancer cells, making PLK1‐mediated post‐transcriptional pathway and ZFP36/TTP phosphorylation promising targets for cancer therapy." (PMID 33411958, 2021). "Moreover, PLK1 is a valuable target for cancer treatment, since its overexpression is correlated inversely with the survival rates of patients in several carcinomas." (PMID 34503223, 2021). "Plk1 siRNA delivered by UQ-body-9R can effectively kill HER2-positive cancer cells." (PMID 33572319, 2021). "Thus, PLK1 appears to induce cell proliferation, and the overexpression of PLK1 is common in malignant tumors." (PMID 33917995, 2021). "Since PLK1 inhibitors such as volasertib and genistein enhance the therapeutic sensitivity of paclitaxel-resistant cancer, we hypothesized that blocking PLK1 would suppress chemoresistance through the downregulation of ABC transporters." (PMID 34503223, 2021). "Drugs with targets such as EGFR, ERBB2, MTOR, PARP2, AURKB, MAP2K1 and PLK1 share more similar profiles, which indicates that the inhibition of these targets has specific effects on the in vitro viability and proliferation of cancer cells." (PMID 33795761, 2021). "Hence, targeting PLK1 by a drug can potentially inhibit or slow down PrCa’s (or any other cancer type’s) metastatic potential." (PMID 34680307, 2021). "Besides the non‐mitotic role, Plk1 is a key regulator of cell‐cycle progression and a key target for the treatment of human cancer." (PMID 34051063, 2021). "A possible explanation for these contradictory functions of PLK1 could be differences in the genetic background of cancer cells and tumor tissue." (PMID 34065956, 2021). "Similarly, v‐Src slightly restores cancer cell viability in cells treated with an inhibitor of PLK1, a core mitotic regulator." (PMID 33465289, 2021). "Recent studies showed PLK1 as a promising target for cancer treatment." (PMID 34003798, 2021). "Importantly, PLK1 is a synthetic lethal target in cancer driven by mutant KRAS, although how PLK1 crosstalks with oncogenic KRAS signaling remains incompletely understood." (PMID 34369083, 2021).
cancer (continued). "PLK1 seems to be a promising target for cancer therapy; its inhibition could repress multiple aberrations by a single agent." (PMID 33411958, 2021). "We found that the deletion of CDC20, CDC25, or PLK1 genes is lethal for all cancer cell lines." (PMID 34887439, 2021). "One possible reason for the unexpectedly high number of plk1 positive cells is a dysregulation in the gene expression, and the messenger would be present in the G1/S phase of the cell cycle, as has been reported in cancer cells." (PMID 33750965, 2021). "Vimentin is a main component of IFs and is found in focal adhesions and could be a substrate of PLK1 during cancer invasion." (PMID 33963314, 2021). "In addition to the mitotic role of Plk1 as a cell‐cycle related kinase, the regulation of its non‐mitotic signaling plays important roles in cancer as well." (PMID 34051063, 2021). "Plk1 contributes to carcinogenesis through communication with multiple pathways promoting cancer." (PMID 34646387, 2021). "Therefore, PLK1 can be considered as a promising primary target candidate for cancer treatment modality, such as PLK1-targeting RNAi-based gene therapy." (PMID 34723284, 2021). "The founding member PLK1 is oncogenic and preclinically validated as a cancer therapeutic target." (PMID 35156101, 2021). "In summary, the simultaneous low expression of PLK1, phosphoMet, SGK2, and SHC1 might be associated with the immune response and tumor cell survival, which could result in poor survival outcomes in cancer progression." (PMID 34575686, 2021). "Therefore, by targeting Plk1, onvansertib inhibits several hallmarks of cancer aggressiveness in vitro." (PMID 34646387, 2021). "Thus, analysis of clinical patient data provides evidence of the relevance of our findings in EGFR-positive LUAD, showing that PLK1 is a strong predictor of poor overall survival in LUAD cancer patients." (PMID 34503223, 2021). "Moreover, FOXM1 binds to known FOXM1 targets in cancer cells: the CCNB1 and PLK1 gene promoters (CCNB1 encodes CYCLINB1 and PLK1 encodes Polo kinase 1, respectively) in WG4 cells as demonstrated by ChIP-qPCR." (PMID 34131149, 2021). "The analysis showed the amplification of CCND1/CDK4/PLK1/CD44 based on percentages of separate genes, with 7% for CCND1, 2.9% for CDK4, 1.7% for PLK1, and 1.8% for CD44 in multiple cancers, including the missense mutation amplifications, deep deletions, and alteration frequencies of these oncogenes." (PMID 34063946, 2021). "Thus, the defective checkpoint recovery pathway has many similarities to BRCA mutation providing further support for the use of PARP inhibitors to treat cancers with dysregulated PLK1 checkpoint recovery pathway." (PMID 33993200, 2021). "Plk1 expression is only occasionally observed in normal thyrocytes, but overexpression of Plk1 is more frequently detected in smaller PTCs, microcarcinomas, and incidental carcinomas." (PMID 34168619, 2021). "To investigate whether the active form of PLK1 triggers invasiveness in cancer, we performed an invasion assay using Matrigel." (PMID 31548612, 2020). "Co‐expression analysis showed PKMYT1 has a strong positive correlation with Polo‐like kinase 1 (PLK1), implying they may cooperate in regulating cancer cell proliferation by synchronizing rapid cell cycle with high quality of genome maintenance." (PMID 31837068, 2020). "PLK1 is highly expressed in several human cancers with poor clinical outcome." (PMID 32438775, 2020). "Because the level of CIN determines its impact in cancer, inhibiting high CIN to intermediate tumorigenic levels is a real risk and altering PLK1 activity could produce unpredictable outcomes." (PMID 33066048, 2020). "Polo-like kinase 1 (PLK1), a mitotic serine/threonine protein kinase, regulates various cellular events throughout the cell cycle and has been shown to potentially be a new target in cancer treatment." (PMID 32486290, 2020).